HGF (hepatocyte growth factor)
Diseases named in the same sentence as HGF in open-access papers (continued):
Sharing a sentence is not in itself a finding about the gene and the disease.
glioma (113 papers, 2008 to 2026). A benign or malignant brain and spinal cord tumor that arises from glial cells (astrocytes, oligodendrocytes, ependymal cells). "Various studies reported that c-Met/HGF signaling is affiliated with increased malignancy and stem cell enrichment in various cancers such as high-grade gliomas, high-risk medulloblastomas, and MYCN-amplified, high-risk neuroblastomas." (PMID 34055785, 2021). "Increased levels of L1CAM-ECD are caused by an upregulation of ADAM 10 in glioma, ovarian cancer and colon and cancer cells, and shedding is promoted by the presence of serum or HGF, hypoxia or apoptotic stimuli." (PMID 31455004, 2019). "Both high HGF expression in tumor cells (59.2%, 45/76) and high PI were significantly associated with high-grade glioma and increased microvessels in tumors (P < 0.05)." (PMID 22741575, 2012). "Recently, TDPs were found to regulate T cell function in the TME; e.g., glioma TDPs inhibited T cell proliferation by releasing prostaglandin E2, serum human leukocyte antigen G, hepatocyte growth factor, and TGF-β and were negatively associated with T cell infiltration." (PMID 36646951, 2023). "Hepatocyte growth factor/scatter factor (HGF/SF) and its cell-surface receptor, the tyrosine kinase c-Met, were found to be closely linked with glioma cell invasion and tumor progression, and c-Met has been widely confirmed as a crucial predictor of GBM patient outcomes." (PMID 33193439, 2020). "He demonstrated that increased expression of HGF may be associated with a worse prognosis in patients with high-grade gliomas." (PMID 32607415, 2020). "Amplification of MET and its ligand HGF has been associated with primary and lower-grade gliomas." (PMID 28458684, 2017). "In human gliomas, the expression of HGF and its receptor, c-Met, is associated with tumor grade." (PMID 22741575, 2012). "The hepatocyte growth factor (HGF) antibody YYB-101 has been demonstrated to have inhibitory effects on the MET pathway in a glioma mouse model." (PMID 41141394, 2026). "The MET proto-oncogene, located on chromosome 7q31, and HGF, located on chromosome 7q21.1, are crucial in glioma cell biology, affecting tumor proliferation, growth, migration, invasion, angiogenesis, and stemness." (PMID 40332008, 2025). "HGF, released by neurons and blood vessels, facilitates glioma invasion and the chemotactic migration of MET-positive cells, while also acting as a chemokine for microglial infiltration in malignant gliomas." (PMID 40332008, 2025). "As such, HGF increases ACSVL3 expression levels in human glioma cells (U373), an enzyme that plays a central role in activating FAs for complex lipid synthesis." (PMID 40524253, 2025). "LD-laden glioma cells augment the secretion of vascular endothelial growth factor (VEGF) and hepatocyte growth factor (HGF), which induces tumor vascularization, glioma-associated microglia/macrophage recruitment, and functional alternations." (PMID 40862760, 2025). "Other factors, such as hepatocyte growth factor, play a significant role in the mitogenesis and mobility of gliomas." (PMID 37713112, 2024). "Microglia can be attracted to glioma cells by the secretion of scatter factor, hepatocyte growth factor and so on." (PMID 39015316, 2024). "The paracrine HGF secretion from neurons greatly facilitated glioma cells’ growth and development and chemotactic invasion in MET-positive cells." (PMID 38201528, 2023). "The signals from c-Met significantly promote the malignant promotion and formation of tumors, including gliomas, via an autocrine/paracrine mechanism activated by the overexpression of c-Met and its ligand hepatocyte growth factor (HGF)." (PMID 38201528, 2023). "Recently, it has been demonstrated in vivo, using syngeneic GL261 mouse model of glioma, and in vitro, using coculture of normal astrocytes and GL261 glioma cells, that upon irradiation normal astrocytes became senescent and release factors, including HGF." (PMID 38293652, 2023).
glioma (continued). "Previous work has demonstrated that radiation indeed stimulates TGF-β signaling in the orthotopic SMA-560 glioma model via hepatocyte growth factor (HGF) and its receptor MET35." (PMID 37996600, 2023). "Microscopy analysis of tumor sections, as well as in vitro and in vivo experiments with anti-HGF agents, have suggested that both autocrine and paracrine signaling of HGF occurs in gliomas." (PMID 36034555, 2022). "The HGF/c-MET pathway has been shown to contribute to anti-cancer therapy resistance in human gliomas." (PMID 36034555, 2022). "Early studies of human primary brain tumor samples have shown increased expression of c-MET and/or HGF in higher grade gliomas, such as glioblastoma multiforme (GBM)." (PMID 36034555, 2022). "The HGF/MET complex can also influence COX-2 expression in glioma cells where complex signaling promotes PGE2 release, up-regulating COX-2 expression." (PMID 36471782, 2022). "Similar to its effects in sarcomas, stimulation with HGF increased glioma cell proliferation, motility, and invasion." (PMID 36034555, 2022). "In glioma cells, for example, HGF drives c-MET to the periplasm of the endosome for prolonged activation of Rac1, resulting in optimum membrane ruffling, cell motility, and invasion." (PMID 35630066, 2022). "Much of the literature discussing the role of HGF/c-MET in glioma is based upon studies of adult primary tumors, or cell lines derived from adult tumors." (PMID 36034555, 2022). "Specifically, PRDX1 forms a heterodimer with p38α MAPK14, stabilizing phospho-p38α in glioma cells and enhancing HGF-mediated signaling." (PMID 34055785, 2021). "The Laszmus studies relied on measuring secretion of HGF proteins in glioma cells using the ELISA method." (PMID 32607415, 2020). "HGF has been proven important in stimulating the proliferation of new blood vessels in glial tumors." (PMID 32607415, 2020). "Significantly increased HGF expression was also found in the endothelial cells of blood vessels in high-grade gliomas and in glial astrocytes found in the invasive glioma growth." (PMID 32607415, 2020). "Twenty glioma samples were examined initially, from which protein extracts were obtained, and elevated HGF were found in the tumor cells." (PMID 32607415, 2020). "When HGF is overexpressed in glioma cells, this functionally increases their tumorigenicity, growth, and angiogenesis." (PMID 33066121, 2020). "The HGF/SF together with c-Met was found upregulated in glioma tissue, positively correlated with the grade of glioma and poor prognosis." (PMID 33511267, 2020). "In this review, we highlight progress made in the understanding of MET signaling in glioma and advances in therapies targeting HGF/MET molecules for glioma patients in recent years, in addition to studies on the expression and mutation status of MET." (PMID 31221203, 2019). "The progress made in understanding of MET signaling in glioma and advances in therapies targeting HGF/MET molecules for glioma patients in recent 30 years were highlighted, in addition to studies on the expression and mutation status of MET." (PMID 31221203, 2019). "In gliomas, HGF/MET signaling has been demonstrated to promote tumor growth and migration via the up-regulation of Cox-2 expression and the stimulation of PGE2 release." (PMID 31221203, 2019). "Apart from autocrine HGF secretion, paracrine HGF secretion from neurons and the vasculature facilitates glioma invasion and augments the chemotactic invasion and proliferation of cells that are MET-positive." (PMID 31221203, 2019). "The overexpression of HGF by glioma cells has been correlated with increased tumor microvascularity, increased tumor grade, and worse prognosis for patients." (PMID 32914058, 2018). "Downregulation of HGF in human-derived glioma cells was also shown to reduce their proliferative and migratory capacity." (PMID 32914058, 2018).
glioma (continued). "While low P311 mRNA levels can be observed in glioma cell lines with a high expression of Met-HGF/SF, a tumor suppressive function for P311 was excluded since P311 overexpression in U118 glioma cells did not interfere with tumor growth in vivo." (PMID 30369881, 2018). "Given their role in mediating migration and invasiveness, resistance to irradiation and maintenance of the glioma SC pool, both HGF/c-MET and TGF-β signaling pathways have been considered as potential therapeutic targets." (PMID 29238047, 2017). "Emibetuzumab has significant anti-tumor efficacy in in vivo HGF-dependent glioma and HGF-independent gastric and NSCLC xenograft tumors." (PMID 28817103, 2017). "In U87MG glioma cells and vascular endothelial cells stimulated by hepatocyte growth factor, platelet-derived growth factor and VEGF, the intracellular domain of NRP1 induces tyrosine phosphorylation of p130Cas, which stimulates growth and invasion of gliomas." (PMID 29088765, 2017). "For example, FAT atypical cadherin 1 (FAT1) and the hepatocyte growth factor (HGF) pathway are both known molecular features of glioma pathogenesis." (PMID 29081735, 2017). "In vitro stimulation of endogenous HGF production by the addition of sialylated glycolipids have also been demonstrated in human glioma cells." (PMID 26848584, 2016). "The most characterized HGF-dependent xenograft model is the U87-MG human glioma cells, which expresses both human MET and HGF29." (PMID 27546726, 2016). "Stimulation of glioma cells with hepatocyte growth factor (HGF), the cognate Met ligand, robustly triggered Met phosphorylation in LN229, U87MG and SD02 GSC in a dose-dependent manner." (PMID 25762646, 2015). "Of note, expression of the hepatocyte growth factor (HGF) receptor MET in VEGFR-2-positive glioma cells was heterogeneous." (PMID 25682871, 2015). "Hepatocyte growth factor (HGF) and Tissue Factor (TF) are two examples of a number of cytokines that show increased serum levels after cerebral ischemia and are known to induce glioma cell migration." (PMID 25966341, 2015). "MET is increasingly recognized as an important target in multiple tumor types, including glioma, and therapeutic antibodies against HGF or the HGF binding site on MET have been developed." (PMID 25862637, 2015). "It is important to note that the RTK c-Met and its ligand hepatocyte growth factor (HGF)/Scatter factor are overexpressed in gliomas and that their expression levels correlate with tumor grade." (PMID 24709958, 2014). "After U373 human glioma cells (c-Met+/HGF−) were treated with HGF for 30 min to activate c-Met, cell lysates were obtained and diluted to a final concentration of 0.2 μg/μL in a kinase reaction mixture." (PMID 24023761, 2013). "Our next aim was to test if ReNcells CX injected into systemic circulation were able to reachintracerebral gliomas and to explore under this condition the expression of HGF, VEGF,zonulin/prehaptoglobin-2 and claudin-5." (PMID 23637756, 2013). "HGF had previously been found to be themost efficient chemo-attractant for NSC produced by glioma cell lines." (PMID 23637756, 2013). "Both SF/HGF and c-Met are overexpressed in human glioblastomas, and these expression levels correlate with glioma malignancy grade and vascularity." (PMID 24294521, 2013). "Thepresence in glioma C6 CM of high amounts of HGF, VEGF, zonulin and PGE2, together withthe low abundance of EGF, promoted ReNcells CX transmigration." (PMID 23637756, 2013). "To further demonstrate the importanceof this factor on glioma-induced transmigration, we added to glioma C6 CM, antibodies with theability to neutralize the bioactivity of HGF and observed a decreased transmigration of ReNcellsCX." (PMID 23637756, 2013). "HGF is a strong stimulator of in vitro glioma cell migration and c-MET expression has also been demonstrated in invasive glioma cells." (PMID 23484006, 2013).
glioma (continued). "We think that in the non-glioma brain sections, HGF was barely detectable andVEGF remained undetectable since these factors were scarcely produced by astrocytes in comparison togliomas as here shown in the corresponding CM." (PMID 23637756, 2013). "We found that the protein level of FLAG-tagged TRIP10 was substantially reduced upon HGF treatment in the U373 glioma cells." (PMID 24023761, 2013). "Specifically, we asked if our platform was capable of detecting changes in the phosphorylation profile of proteins in glioma xenografts upon inhibition of c-Met signaling using a previously validated neutralizing anti-HGF monoclonal antibody (L2G7)." (PMID 24023761, 2013). "Amplification of the c-MET gene (located on chromosome 7) is seen in glioblastomas and both c-MET and HGF are frequently overexpressed in glioma specimens and cell lines." (PMID 23484006, 2013). "This study indicated that there was significant correlation among tumor cell-derived HGF, cell proliferation and microvessel proliferation in gliomas." (PMID 22741575, 2012). "Gene transfer of HGF to glioma cells enhances their tumorigenicity, tumor growth and tumor-associated angiogenesis." (PMID 22741575, 2012). "The systemic administration of L2G7, another anti-HGF antibody from Galaxy Biotech, translated into the induction of regressions of glioma xenografts." (PMID 22567028, 2012). "U87MG glioma cells were transfected with short interference (si)-RNA for HGF, and the cell viability, migratory ability and chemosensitivity to cisplatin were evaluated in vitro." (PMID 22741575, 2012). "Amgen has recently reported the generation of fully human monoclonal antibodies against HGF that exhibit therapeutic potential in mice bearing subcutaneous xenografts of human glioma cell lines with an HGF-dependent autocrine loop." (PMID 22567028, 2012). "We measured c-MET pY1003 levels by immuno-precipitation in lysates prepared from the Ln18, Ln229, U118, U138, and U87MG glioma cell lines to compare with the HGF/c-MET levels we detected using the VeraTag FFPE assay format." (PMID 21283737, 2011). "These measurements correlated well with the HGF ELISA measurements we obtained using the corresponding glioma cell lysates (Fig. 5Bii) and are in agreement with previous reports on endogenous HGF expression in HGF in U138 and U118 cells." (PMID 21283737, 2011). "To assess endogenous levels of HGF/c-MET ligand-receptor complexes in glioma cells, we used SPPICE to characterize Ln18, Ln229, and U118 cell lysates." (PMID 21283737, 2011). "We assessed endogenous level of HGF in FFPE pellets generated from a panel of glioma cell lines (Ln229, Ln18, U138, U118, and U87MG cells)." (PMID 21283737, 2011). "In several glioma cells that exhibit activation of HGF/c-MET signaling, we detected high levels of c-MET (pY1003) phosphorylation that are likely modulated through a c-MET and HGF autocrine loop." (PMID 21283737, 2011). "Next, we sought to correlate the presence of autocrine driven HGF/c-MET complexes in glioma cells with a direct indicator of c-MET activation." (PMID 21283737, 2011). "DBTRG-05MG is a human glioma cell line that is highly invasive in vitro in response to hepatocyte growth factor (HGF), but grows poorly as SQ tumor xenografts." (PMID 19055779, 2008). "Chemoattractants for microglia released by macrophages include Hepatocyte growth factor/scatter factor released by glioma cells, while CXCL12 (SDF-1) is also a potent microglia and macrophage recruiting molecule, especially for attracting TAMs to hypoxic areas." (PMID 38672638, 2024). "HGF then activates the Met receptor on glioma, promoting tumor invasiveness." (PMID 38293652, 2023). "In addition, glioma cells also secrete hepatocyte growth factor (HGF) and scatter factor (SF) as chemo-attractants for microglia, but this has only been validated in a microglial cell line." (PMID 35600367, 2022).
glioma (continued). "In addition to autocrine HGF, paracrine HGF can also promote the invasion of glioma and enhance the chemotactic invasion and proliferation of the MET-positive cells." (PMID 35935338, 2022). "MET encodes the receptor for hepatocyte growth factor (HGF) and has great importance in the migration and invasiveness of glioma cells, such as in response to irradiation, inhibition of angiogenesis and hypoxia, and has a critical role in therapeutic resistance and recurrence of GBM." (PMID 35628161, 2022). "Mutations in isocitrate dehydrogenase (IDH), vascular endothelial growth factor (VEGF), epidermal growth factor (EGF), platelet-derived growth factor (PDGF), and hepatocyte growth factor (HGF) have been recognized to be involved in aberrant proliferation of glioma cells." (PMID 35922753, 2022). "In the meantime, HGF also acts as a chemokine of microglia and may be related with the infiltration of glioma." (PMID 35935338, 2022). "Overexpression of HGF/MET axis leads to glioma formation in mice." (PMID 34806012, 2021). "We found that the expression of STAT5b, a transcription factor that could be phosphorylated in EGF or HGF dependent manner and promoted the malignant progression of gliomas 29, 43, was abnormally upregulated in TMZ resistant cells." (PMID 32194873, 2020). "Additionally, the RTK c-Met and its ligand hepatocyte growth factor (HGF)/Scatter factor are overexpressed in gliomas and they have been shown to play a role in cell proliferation, invasion, angiogenesis and survival in several cancers." (PMID 31467533, 2019). "U87MG is an aggressive glioma that possesses autocrine HGF c-Met signaling." (PMID 26879245, 2016). "Glioma cell / endothelial cell co-cultured aggregates displayed a greatly altered pattern of gene expression compared to glioma-only aggregates, with many of the genes putatively implicated in VM including NOTCH4, TGFβ, HGF and CD31 being significantly downregulated." (PMID 26203665, 2015). "This implies that the Plexin-B2/Met synergy may become biologically relevant when glioma cells encounter sub-threshold levels of HGF, a situation conceivably occurring at the invasive front of gliomas." (PMID 25762646, 2015). "Hepatocyte growth factor/scatter factor acts exclusively through the tyrosine kinase receptor c-Met and expression of both the soluble ligand and receptor has been demonstrated in both ex vivo human glioma and TAM cells." (PMID 23737783, 2013). "HGF enhances angiogenesis via the induction of growth, movement and morphogenesis of endothelial cells (EC) in a culture system and in a mouse model of glioma." (PMID 23296269, 2013). "Hepatocyte growth factor (HGF)/scatter factor (SF), which plays a role in glioma motility and mitogenesis, may be one chemokine responsible for the microglia infiltration in malignant gliomas." (PMID 23983766, 2013). "In the in vivo experiments we demonstrated the capacity of ReNcells CX injectedinto systemic circulation, to migrate to intracerebral glioma C6 and confirmed our invitro findings, by showing an increased expression of HGF, VEGF and zonulin in theintracranial tumor." (PMID 23637756, 2013). "The amount of HGF was found to be 3.2 times higher in glioma C6 CM than in astrocyteCM." (PMID 23637756, 2013). "Additionally, signalling pathways that are commonly disinhibited in gliomas including the TGFβ/Akt and HGF pathway are also known to influence wnt signalling." (PMID 22919349, 2012). "In addition, Arf6 is also found to form complexes with Rac1 and IQGAP1 in glioma cells upon HGF stimulation, and IQGAP1 is essential for Arf6-induced Rac1 activation and cell migration." (PMID 22701712, 2012). "The relationship, if any, between HGF and chemoresistance in gliomas needs to be verified." (PMID 22741575, 2012). "However, only histological grading (P = 0.004) and high-expression of HGF (P = 0.008) emerged as independent prognostic factors for the overall survival of glioma patients." (PMID 22741575, 2012).